GRK5 (G protein-coupled receptor kinase 5)
Diseases named in the same sentence as GRK5 in open-access papers (continued):
Sharing a sentence is not in itself a finding about the gene and the disease.
heroin dependence (1 paper, 2022). Physical and psychological dependence on the drug heroin. "Genetic variants at the GRK5 gene have been associated with the regulation in methadone dosage in heroin dependence." (PMID 36745154, 2022).
liver cancer (1 paper, 2024). An epithelial or non-epithelial malignant neoplasm that arises from the liver. "Unlike the main location of GRK5 expression in the nuclear membrane, previous research has shown that the main location of GRK4 expression in HCC was cell plasma, although the detailed mechanism of GRK4 regulation of liver cancer remains to be elucidated." (PMID 38638965, 2024).
multiple myeloma (1 paper, 2025). "GRK6, a close homolog of GRK5, is considered as a possible therapeutic target for multiple myeloma." (PMID 40388590, 2025).
osteoarthritis (1 paper, 2021). A noninflammatory degenerative joint disease occurring chiefly in older persons, characterized by degeneration of the articular cartilage, hypertrophy of bone at the margins and changes in the synovial membrane. "Recently, it has been demonstrated that G protein-coupled receptor kinase 5 (GRK5) plays a pathogenic role in the development of osteoarthritis (OA) through catabolic responses in chondrocytes mediated by NF-κB signalling." (PMID 34006987, 2021).
prediabetes (1 paper, 2014). "Association of GRK5 intronic (CA)n repeat polymorphisms with prediabetes and T2DM (n = 1164)." (PMID 24594703, 2014). "Consequently, the (CA)n polymorphism of GRk5 rs10886471 has a risk-protective yin–yang effect against prediabetes and T2DM." (PMID 24594703, 2014).
psychosis (1 paper, 2024). "Association analyses of age-at-onset, number of mood episodes, and presence of psychosis, substance abuse and/or suicidal ideation suggested modest contributions of genes such as RTN4, XKR4, NRXN1, NRG1/3 and GRK5 to disease characteristics." (PMID 38570518, 2024).
pulmonary embolism (1 paper, 2024). The obstruction of the pulmonary artery or one of its branches by an embolus, sometimes associated with infarction of the lung. "We therefore used platelet-specific GRK5 mutant mice and models of thrombosis and pulmonary embolism." (PMID 39309233, 2024). "In addition, platelet GRK5 mutant mice had increased thrombin but not collagen-induced thrombus burden in a mouse model of pulmonary embolism." (PMID 39309233, 2024).
pulmonary regurgitation (1 paper, 2019). "mRNA levels for β-adrenoceptors and G-protein coupled receptor kinases GRK2, GRK3 and GRK5 in peripheral blood mononuclear cells from patients with pulmonary regurgitation under treatment (n = 9) or not (n = 14) with betablockers." (PMID 30837872, 2019).
renal cell carcinoma (1 paper, 2021). "Further, Kaplan–Meier survival analysis showed that GRK5 high expression was associated with shorter OS, but not RFS, which is consistent with the previous reports that GRK5 high-expression NSCLC or renal cell carcinoma patients had a worse OS rate than the low-expression patients." (PMID 35223984, 2021).
rheumatoid arthritis (1 paper, 2021). A chronic, systemic autoimmune disorder characterized by inflammation in the synovial membranes and articular surfaces. "Immunohistochemically, rheumatoid arthritis (RA) synovium had a significantly higher proportion of GRK5-positive cells in the synovial lining layer than healthy control synovium." (PMID 34006987, 2021).
synovitis (1 paper, 2021). Inflammation of a synovial membrane. "This study aimed to reveal the characteristics of GRK5 in human synovium and the functional involvement of GRK5 in the development of synovitis in a murine model of collagen antibody-induced arthritis (CAIA)." (PMID 34006987, 2021).
testicular cancer (1 paper, 2025). A primary or metastatic malignant neoplasm that affects the testis. "Cellular functional assays revealed that GRK5 knockdown significantly attenuated the malignant phenotype of testicular cancer cells, as evidenced by reduced proliferative capacity and invasive potential." (PMID 40722845, 2025). "Through bioinformatics screening and experimental validation, we have demonstrated that GRK5 promotes the proliferation, migration, and invasion of testicular cancer, while simultaneously suppressing tumor immunity." (PMID 40722845, 2025). "Complementary immunological validation established that specific targeting of GRK5 with the selective antagonist GRK5-IN-2 disrupts immune evasion pathways in testicular cancer, as quantified by T-cell-mediated cytotoxicity." (PMID 40722845, 2025).
cancer (26 papers, 2009 to 2026). A tumor composed of atypical neoplastic, often pleomorphic cells that invade other tissues. "Both GRK6 and GRK5 have been shown to regulate canonical Wnt signaling, with both genes implicated in increased cellular proliferation, migration, and aggressiveness in a variety of cancer types." (PMID 40424447, 2025). "Thus, it is likely to speculate that GRK5 down-regulation of GPCRs could be one of the mechanisms that ensure a proliferative advantage to cancer cell, because the loss of GRK5 activity, allows the cell to escape to a control mechanism of the cellular growth." (PMID 27326393, 2016). "G protein-coupled receptor kinase 5 (GRK5) is an important therapeutic target involving cardiovascular diseases, cancer, and inflammatory disorders." (PMID 41977505, 2026). "Subsequent functional assays revealed that among the five target genes, GRK5 had the most pronounced impact on cancer cell proliferation, invasion, metastasis, and immortality." (PMID 40722845, 2025). "The potential role of GRK5 DNA methylation in the progression/prognosis of cancer has been rarely studied." (PMID 34034702, 2021). "There was a significant difference on the GRK5, ACTC1, and GRK5/ACTC1 expression between the cancer and paratumor tissues (p < 0.0001, p < 0.0001, p < 0.0001)." (PMID 35223984, 2021). "For this reason, in this review article, we will inform the readers of the most recent evidence that supports the importance of targeting GRK5 to prevent the development or progression of cancer, cardiovascular, and neurological diseases." (PMID 33671974, 2021). "While GRK5 has been extensively studied for its role in the pathogenesis of cardiovascular disease, only in recent years has its role in cancer biology been brought to light." (PMID 32363002, 2020). "While GRK5 has been extensively studied for its role in heart disease, the role of GRK5 in cancer pathogenesis is poorly characterized." (PMID 32363002, 2020). "The studies characterizing the role of GRK5 in cancer pathogenesis to date have primarily investigated the functional requirement of its kinase activity." (PMID 32363002, 2020). "In this study we demonstrate that a decreased GRK5 expression induced by knock-down experiments or sunitinib treatment hampers the migration of cancer cell lines." (PMID 31664083, 2019). "Specifically, recent studies have demonstrated that GRK5 is required for cancer cell cycle progression." (PMID 29463786, 2018). "The RH domain of GRK5 is an effective modulator of cancer growth through the inhibition of NFκB activity." (PMID 30524659, 2018). "Human studies have suggested that GRK5 is increased in expression and activity in various cardiac diseases and GRK5 has recently been designated as a potential therapeutic target in cancer due to its anti-tumor effect when inhibited." (PMID 30618771, 2018). "Altogether, these findings support the proof of concept that GRK5 inhibits tumor growth in different cancer cells, through the phosphorylation of GPCR on plasmamembrane." (PMID 27326393, 2016). "We provide evidence using two sets of experiment: the first set, gathered through the overexpression of GRK5-RH by AdGRK5-RH, provides the proof of concept that GRK5-RH is able to inhibit cancer growth." (PMID 19900276, 2009). "Here we demonstrated that GRK5-RH is able to induce apoptotic events in our model of cancer as evidenced by increased levels of the active form of caspase 3 (both by western blot and histological analysis) and Annexin V staining." (PMID 19900276, 2009). "We recently demonstrated that the RH domain of GRK5 (GRK5-RH) inhibits NFκB, thus we evaluated its effects on cancer growth." (PMID 19900276, 2009). "In addition, detection of GRK5 expression provides a target for determining the effectiveness of drugs and determining patient prognosis in cancer." (PMID 33841542, 2020). "This suggests that treatments with PTX could be more successful among cancers with lower GRK5 protein expression." (PMID 33182737, 2020).
cancer (continued). "The decrease in its expression by GRK5 KD therefore directly impacts the migration of cancer cells." (PMID 31664083, 2019). "Indeed, GRK5 seems to have a double effect on cancer being an inhibitor or inducer of cancer progression depending on its subcellular localization and cancer type." (PMID 30524659, 2018). "Besides the inhibitory effect of GRK5 on tumor growth, GRK5 is also able to promote cancer cell proliferation." (PMID 29463786, 2018). "Indeed, RH10 peptide, comprising only 10 amino acids of GRK5-RH sequence, is able to reduce cancer cells proliferation in vitro and to inhibit tumor growth in vivo in a dose-dependent manner by inhibiting NFκB activity." (PMID 30524659, 2018). "Several studies indicated that GRK5 functions as negative regulator in some types of cancers." (PMID 29463786, 2018). "Thus, GRK5 is involved in the development and progression of several pathological conditions including cancer." (PMID 27326393, 2016). "Given these different effects of GRK5 on tumor growth, targeting GRK5 could be an useful anti-cancer strategy, for specific tumor types." (PMID 27326393, 2016). "GRK5 inhibits cancer cell proliferation in the Kaposi’s sarcoma." (PMID 27326393, 2016). "The proof of concept that GRK5 is involved in the regulation of cancer progression derives from the discovery that GRK5 was part of a subset of gene targets required for mitotic progression in human cancer cells." (PMID 27326393, 2016). "Several studies show that GRK5 may be a negative regulator of cancer cell proliferation, mainly through its ability to desensitize GPCR on plasma membrane." (PMID 27326393, 2016). "However, the effectS of GRK5 on cancer cell proliferation are controversial depending on its subcellular localization and on the type of cancer." (PMID 27326393, 2016). "Moreover, we will debate about the potential therapeutic strategies for cancer focused on GRK5 as main target." (PMID 27326393, 2016). "TGPSM2 and GRK5 are members of G-protein signaling pathway important in cancer progression." (PMID 27822437, 2016). "All these findings suggest that targeting GRK5 could be an useful anti-cancer strategy, for specific tumor types." (PMID 27326393, 2016). "Among the regulator of cell cycle progression in cancer, GRK5 could represent a candidate molecule, given its nuclear localization and the identification of new nuclear substrates of this kinase." (PMID 27326393, 2016). "Little is known about the nuclear effects of GRK5 in cancer." (PMID 27326393, 2016). "Additionally, the inclusion of a selective GRK5 inhibitor in combination with PTX could increase cancer cell death." (PMID 33182737, 2020). "Furthermore, we performed an expression analysis of all GRK4-family members, GRPR and GRPR down-stream signalling components to elucidate whether the effect of sunitinib on cancer cell migration is based on the GRK5-GRPR signalling cascade." (PMID 31664083, 2019). "Furthermore, we observed that treatment with the multispecific kinase inhibitor sunitinib decreases the cancer cell migration by reducing the GRK5 expression levels resulting in attenuated GRPR signalling, depicting a novel mechanism of action of a well-known drug." (PMID 31664083, 2019). "Thus, the aim of this study is to identify the minimum effective sequence of the RH domain of GRK5 that could become a useful peptide-based drug in the treatment of cancer by means of NFκB inhibition." (PMID 30524659, 2018). "In summary, GRK5 is involved in the development and progression of several human diseases including cancer, although its role in tumorigenesis is still complex and ambiguous based on its opposite effects, cancer types, kinase activity, and protein subcellular localization." (PMID 29463786, 2018).
cancer (continued). "We found that GRK5 is highly expressed in NSCLC cancerous tissues compared with normal non-cancerous tissues, whose high expression in NSCLC patients correlates with worse prognosis and survival rate than low expression patients, and is frequently mutated in NSCLC cancer tissues." (PMID 29463786, 2018). "GRK5 can regulate GPCR signaling, which correlates with various diseases like cardiac dysfunction, diabetes, hypertension, Alzheimer’s disease, and cancers." (PMID 35223984, 2021). "Recent studies provide evidence that phosphorylation of serine 21 of HDAC6 by G protein-coupled receptor kinase 5 (GRK5) promotes deacetylase activity in ovarian (HeLa) and breast (MDA MB 231) cancer cell lines." (PMID 32823874, 2020). "We have previously identified a new inhibitor of NFκB activity, the RH domain of G protein-coupled receptor kinase 5 (GRK5), that is effective in several cell types, including cancer cells." (PMID 30524659, 2018). "G protein-coupled receptor kinase 5 (GRK5) has been demonstrated to play pivotal roles in both development and progression of several pathological conditions including cancer." (PMID 29463786, 2018). "Thus the use of these compounds could be effective to induce GRK5 expression in cancer." (PMID 27326393, 2016). "To close up to a more pharmacological tool, we designed a protein (TAT-RH) reproducing the RH domain of GRK5, engineered to be actively transported into the cells through the retroviral TAT sequence and tested its anti-cancer property." (PMID 19900276, 2009). "In order to verify reliable GRSDMs, 22 specific DNA methylation genes related to prognosis obtained in the training set were verified on 11 sets of GEO data, and 8 of the specific DNA methylation genes (DGRK, F2RL3, GRK5, NECAB2, OR1C1, OR2L13, OR6F1, and PIK3R6) had been verified in pan-cancer." (PMID 35885996, 2022). "It is known that the activation of these receptors is regulated by GRK5 in different cell types, although it was never explored in cancer cells." (PMID 27326393, 2016). "An innovative strategy has been proposed that is specific for cancer and is based on a competitive interaction with GRK5 cytosolic substrates rather than inhibition of its activity, the TAT-RH peptide." (PMID 27326393, 2016). "Another interesting interacting protein of GRK5 is STK38 which is identified in GRK5 immunocomplex in cancer cell lines (MDA-MB-231 cells), but not in normal cells (HUVEC)." (PMID 22952844, 2012). "Our data suggest that GRK5-RH inhibition of NFκB is a novel and effective anti-tumoral strategy and TAT-RH could be an useful tool in the fighting of cancer." (PMID 19900276, 2009). "GRK5 and HDAC6 form a signaling complex where GRK5 phosphorylates HDAC6 at Ser-21, promoting deacetylase activity, which may contribute to PTX resistance in cancer cells." (PMID 33182737, 2020). "However, this inhibitor is not strictly selective for GRK5, and it has not been tested in cancer yet." (PMID 27326393, 2016). "However, amlexanox is not GRK5 selective and yet has to be tested in cancer-related paradigms." (PMID 30618771, 2018). "Indeed, it has been demonstrated that in the nucleus GRK5 interacts with and phosphorylates nucleophosmin (NPM1), a multifunctional protein involved in the regulation of cell cycle, centrosomal duplication and apoptosis, that is overexpressed in several cancer types." (PMID 27326393, 2016). "We synthesized a protein reproducing the RH domain of GRK5, engineered to be actively transported into the cells by means of TAT domain without the support of other vehicles and tested its anti-cancer property." (PMID 19900276, 2009).